TNF (tumor necrosis factor)
Diseases named in the same sentence as TNF in open-access papers (continued):
Sharing a sentence is not in itself a finding about the gene and the disease.
AIDS (continued). "HIV/AIDS-associated production and release of proinflammatory cytokines, including TNF-α and IFN-γ, may also disrupt tight junctions of oral epithelial cells and lead to paracellular penetration of HIV-1." (PMID 37239115, 2023). "In a study involving macaques with SIV-induced encephalitis, rapid progression to Acquired Immune Deficiency Syndrome (AIDS) correlated with an increase in IL-1β, IL-2, IL-6, IL-10, and TNF-α." (PMID 34784367, 2021). "Moreover, TNF-α transcripts are abundantly expressed in colonic mucosa from untreated AIDS patients with CMV colitis and are associated with macrophage-like cells containing cytomegalic inclusions." (PMID 28241080, 2017). "Thus, chronic diarrhea and/or weight loss in African AIDS patients is associated with increased levels of macrophage related cytokines (TNF-α and IL-1β) and chemokines (CCL2) compared to HIV-negative healthy controls." (PMID 26475133, 2015). "The synergy between HIV tat protein and TNF-α detected in elevated levels in association with HIV/AIDS increases β2 integrin expression in monocytes; these responses may lead to active translocation of monocytes from the circulation into tissue sites where they differentiate into LCs." (PMID 37239115, 2023). "This profile of circulating cytokines has similarities with those detected in other monogenic AIDs, specially associated with increased pyroptosis (inflammasomopathies, TNF-receptor-associated periodic syndrome), which are usually well controlled with anti-IL-1 and/or anti-TNF." (PMID 35716229, 2022). "Patients with AIDs often have elevated levels of pro-inflammatory cytokines such as tumor necrosis factor-α, IL-1, IL-6, and chemokines in their bloodstream." (PMID 41239630, 2025). "Further studies of WF10 in patients with advanced AIDS also confirmed the intermittent dosing regimen and documented the regulation of monocyte expression of activation antigens and TNF-α RNA after a single 5-day cycle of the drug." (PMID 41463070, 2025). "Clinical trials further support CUR’s anti-inflammatory properties, showing reductions in markers such as C-reactive protein and TNF in people living with HIV/AIDS (PLWHA)." (PMID 40309788, 2025). "Solid organ or bone marrow transplantation recipients, patients receiving tumor necrosis factor (TNF) inhibitors, and those with malignancy or AIDS are at higher risk of severe disease." (PMID 39469362, 2024). "Inflammatory factors such as tumor necrosis factor- α (TNF-α) and interleukin-6 (IL-6) are elevated in patients with HIV infection/AIDS, strongly suggesting a possible association between disease progression and inflammatory response." (PMID 40217405, 2024). "For example, TNF and IL families play an important pro-inflammatory activity in AIDs, so many treatment strategies for AIDs involve anti-inflammatory therapy, corticosteroids reduce inflammation." (PMID 37859999, 2023). "We have previously shown that serum levels of TNFα are significantly elevated in HIV+ individuals part of the MWCCS, and these elevated levels are strongly associated with increased risk of AIDS-NHL." (PMID 37809067, 2023). "The TNF, IFNs, and the IL-1 family are three of the key cytokine pathways involved in the pathophysiology of AIDs." (PMID 36876221, 2023). "The absence/reduction of serum TNFα, G-CSF, GM-CSF and VEGF predispose AIDS patient with CM to developing subsequent CM-IRIS." (PMID 36310879, 2022). "Given the role of the proinflammatory cytokine tumor necrosis factor (TNF) in the pathogenesis of many AIDs, anti-TNF agents are widely used." (PMID 36362622, 2022). "At the same time, the secretion of cytokines such as IFN-α, IL-2, IL-4, IFN-γ, and TNF-α, are beneficial to delay the disease progression of AIDS." (PMID 35211115, 2022). "Of these, TNF-α, IL-6, IL-8 and IP10 are associated with prognoses in patients with HIV/AIDS cryptococcal meningitis and IL-6 is also involved in anticryptococcal drug resistance." (PMID 36310879, 2022).
AIDS (continued). "In the clinic, some cytokines induced by TLRs are immunotherapeutic targets in AIDs, such as TNF-α, interleukin (IL)-6, interferon (IFN)-α, and IL-1β." (PMID 35126357, 2021). "This represented a significant limitation of TNFα inhibitors in the treatment of polygenic AIDs, such as SJIA or AOSD." (PMID 33708123, 2020). "TNFα inhibitors, on the other hand, treat efficiently articular manifestations but often fail to reduce systemic features in monogenic AIDs." (PMID 33603750, 2020). "Whilst the use of steroids to treat AIDs induced potential severe SCD-related complications, which justified associated chronic red blood cell transfusions, other treatments such as anti-TNF agents were well tolerated." (PMID 29343274, 2018). "The absence/reduction of serum pro-inflammatory cytokines such as TNFα, G-CSF, GM-CSF and VEGF (vascular-endothelial growth factor), and increase in serum IL-17 and IL-4, predispose AIDS patient with CM to developing subsequent CM-IRIS." (PMID 29333430, 2017). "A decrease of miR-146a level results in increases of type I IFN and pro-inflammatory cytokines, such as IL-1β and TNF-α, which are involved in the pathogenesis of various AIDs." (PMID 29190882, 2017). "The ability to produce TNFα, IL-8, IL-6 and IP10 cytokines was associated with improved outcome in AIDS patients with CM." (PMID 29333430, 2017). "In AIDS-KS, there is a notable increase in inflammatory cytokines such as tumor necrosis factor a (TNF-a), interferon γ (IFN-γ, interleukins 1 and 6 (IL-1 and IL-6)." (PMID 26913028, 2016). "IHC staining indicated that there was a marked increase in proinflammatory cells expressing IL-1β (median 174 vs. 75 cells/0.8 mm2, p = 0.04) and TNF-α (median 226 vs. 107 cells/0.8 mm2, p = 0.01) in the colon of AIDS patients compared to healthy controls." (PMID 26475133, 2015). "LPS stimulation of total MMC from AIDS patients induced a further increase in TNF-α (median: 17.9 vs 31.8 pg/mL in unstimulated vs. stimulated MMC, respectively, p = 0.031) and IL-6 (median: 19.3 vs 45.46 pg/mL, respectively, p = 0.006) secretion." (PMID 26475133, 2015). "Ex vivo studies of total MMC (containing CD14+ macrophages) isolated from the colon of AIDS patients indicated that these cells secreted increased levels of TNF-α, IL-6, CCL2 and CXCL10 compared to HIV-negative controls." (PMID 26475133, 2015). "Consistent with IHC results, there was a significant increase in TNF-α (FC 7.11, p = 0.05) and IL-1β (FC = 4.27, p = 0.05) mRNA in AIDS patients compared to controls." (PMID 26475133, 2015). "High producer haplotype, CAG of TNF-α gene associates with enhanced apoptosis of lymphocytes in HIV-1 infected individuals, hence faster progression to AIDS." (PMID 24837009, 2014). "CHR and HI individuals as well as CT/AIDS and OT patients, produced 4326.93 pg/mL, 2834.21 pg/mL, 8480.00 pg/mL and 9827.76 pg/mL of TNF-α, respectively." (PMID 25352834, 2014). "Lower TNF-α level (992.71 pg/mL) produced from cells collected from CHR were shown when compared with CT/AIDS and OT patients (2564.54 pg/mL and 2352.52 pg/mL, respectively)." (PMID 25352834, 2014). "Inflammatory cytokines such as TNF-α are elevated in patients with AIDS, and these particular cytokines are also involved in monocyte-macrophage differentiation as well as activation of HIV-1 gene transcription." (PMID 24886416, 2014). "An alternative possibility is that they represent “unmasking” of histoplasmosis at the nadir of the TNF blocker effect, as described in patients with AIDS after they start antiretroviral therapy." (PMID 25379301, 2013). "PBMCs from healthy donors secreted elevated levels of IFN-γ and TNF-α when challenged in vitro with killed R. equi, whereas the release of both cytokines was impaired in supernatant cultures from AIDS patients." (PMID 18475656, 1995).
AIDS (continued). "AIDS progression is strongly correlated with inflammatory markers and chronic immune activation, and upregulated expression of pro-inflammatory cytokines such as TNF and IL-6 has been documented both in vitro and in vivo during HIV-1 infection." (PMID 39459974, 2024). "outbreaks demonstrated an increased risk of death associated with advanced AIDS (CD4 counts <75 mm3), immunocompromised states (such as solid organ transplantation), chronic renal disease, and prolonged use of corticosteroids or tumor necrosis factor (TNF) antagonists." (PMID 36602962, 2023). "Children living with HIV/AIDS, having a history of exposure to pulmonary TB cases, initiating anti-tumor necrosis factor therapy, receiving organ or hematologic transplantation, and patients with end-stage renal failure are at high risk of TB infection or progressingto active TB disease." (PMID 38093183, 2023). "Theoretically, the role of TNF-α in HIV/AIDS suggests that anti-TNF-α therapy may contribute to treatment." (PMID 35990692, 2022). "TNF-α also plays a key role in the pathogenesis of HIV/AIDS." (PMID 35990692, 2022). "In this connection, PML has also been diagnosed in patients with autoimmune rheumatic diseases, albeit not as frequently as in HIV/AIDS patients, and anti-TNFα treatment was associated with a low incidence of PML in these patients." (PMID 30372487, 2018). "Measurements of TNF levels vary in patients with AIDS and they often have low levels of TNF." (PMID 29553046, 2018). "According to this theory, immune activation (following an infection such as HIV/AIDS) releases pro-inflammatory cytokines such as interferon gamma (IFNγ), interleukin 6 (IL-6), and tumor necrosis factor alpha (TNF-α) which induce secretion of indoleamine 2, 3-dioxygenase (IDO)." (PMID 29298663, 2018). "Collectively, these findings indicate that macrophages in the colon of African AIDS patients with diarrhea and/or weight loss have an activated CD14+ phenotype and express pro-inflammatory cytokines (TNF-α, IL-1β) that are known to be induced by LPS–mediated activation of CD14+ macrophages." (PMID 26475133, 2015). "Therefore, this approach allowed us to identify important differences involving IP-10, TNF-α, IL-6, IFN-α, and IL-10 interactions that play important roles in AIDS and are a hallmark between the two treatments here analyzed." (PMID 26684789, 2015). "TNF-α plays an important role in progression to AIDS for HIV-1-infected patients." (PMID 24714696, 2014). "Cerebrospinal fluid from most of the patients with AIDS has increased levels of TNFα." (PMID 21599974, 2011). "Cerebrospinal fluid from most patients with AIDS shows an increase in TNFα." (PMID 21599974, 2011). "We propose that the coordinated upregulation of CDKN1A, IER3, GADD45B and TNF as well as the positive regulation of calcium-dependent signaling could be involved in the mechanisms leading to the slower progression to AIDS and HIV control concomitantly observed in EC-LTNPs." (PMID 31582776, 2019). "However, immunocompromised individuals, including HIV/AIDS patients, solid-organ transplant recipients, bone marrow transplant recipients, patients receiving tumor necrosis factor (TNF) inhibitors, and patients with cellular immune dysfunction are at increased risk for disseminated infection." (PMID 29849657, 2018). "Furthermore, in AIDS-KS tumor biopsies high expression of glucocorticoid receptors (GRs) was detected as well as an up-regulation of GRs by KS-growth-promoting factors like tumor necrosis factor-α." (PMID 25077599, 2014). "Severe and disseminated infection primarily occurs in people living with HIV/AIDS (PLWHA), solid organ transplant recipients, or those on immunosuppressive medications such as corticosteroids or tumor necrosis factor alpha (TNF-α) inhibitors." (PMID 40137234, 2025). "Patients living with HIV/AIDS exhibit enhanced activation of NF-κB and TNF-α mRNA transcription following cryptococcal infection, which can regulate the expression of TNF-α." (PMID 37251371, 2023).
AIDS (continued). "Patients with extrapulmonary visceral organ or disseminated NTM disease are almost always frankly immunocompromised, such as those receiving tumor necrosis factor (TNF) antagonist therapy, organ transplantation, and having untreated AIDS." (PMID 35889173, 2022). "TNF-α is an important inflammatory pathway in the pathogenesis of RA, and its levels in HIV-infected patients are also suggestive of HIV/AIDS pathogenesis." (PMID 35990692, 2022). "Compared to healthy individuals, HIV/AIDS patients with cryptococcal meningoencephalitis displayed higher CSF levels of IFN-γ, TNF-α, IL-6, IL-7, IL-8, IL-10, IL-12p40, IL-15, IL-18, and CCL2." (PMID 36557672, 2022). "Clinical studies demonstrated that higher levels of IFN-γ and TNF-α in cerebrospinal fluid (CSF) and/or serum were correlated to a better fungal clearance and enhanced survival of HIV/AIDS patients co-infected with C. neoformans." (PMID 36557672, 2022). "Elevation of TNF-α, IL-6, and downregulation of IFN-γ, as already reported in AIDS patients, marked upregulation of miRNA 125b-5p." (PMID 32126572, 2020). "Those with statistically significantly higher values in the AIDS-KS cases were IFN-γ, MCP-1, IFN-γ, sIL-6R, sIL-2Rα, IL-10, BLC-BCA1, CD27, sTNFR-2, sCD14, TNF-α, and IP-10." (PMID 33521162, 2018). "IFN-γ, sIL-2Rα, sIL-6R, IL-10, IP-10, TNF-α, MCP-1, sCD14, BLC-BCA1 and sTNFR-2 were found to be higher in the subsequent AIDS-KS cases than those unaffected." (PMID 33521162, 2018). "sIL-2Rα, sIL-6R, IL-10, IP-10, MCP-1, TNF-α, eotaxin, BLC-BCA1, CD27 and sTNFR-2 were all statistically significantly higher in AIDS-KS than controls." (PMID 33521162, 2018). "There is a report demonstrating that the levels of TNF-α, IL-1β and IL-8 are significantly higher in asymptomatic HIV-infected African women than women living with AIDS, suggesting the role of cytokines in early phase of HIV infection." (PMID 25879453, 2015). "Tissue and plasma samples of hosts express high levels of TNF-α, contributing to fever, anorexia, and other symptoms of HIV/AIDS." (PMID 22164280, 2011). "In the present, it was possible to observe higher serum levels of TNF-α in men living with HIV/AIDS without lipodystrophy, compared with men with HALS." (PMID 34957175, 2021). "In this work, cell-free mtDNA in CSF samples has been inversely associated with peripheral and CSF inflammation [MCP-1 in CSF, and tumor necrosis factor-α (TNF-α) and IL-8 in plasma] under virologically effective ART (also after adjustment for past AIDS diagnosis)." (PMID 31427955, 2019). "However, at the time of CM-IRIS, there are significant increases in CSF levels of IFNγ, TNFα, G-CSF, VEGF and eotaxin compared to baseline levels within AIDS patients." (PMID 29333430, 2017). "TNF-α+ and IL-1β+ CD68-positive macrophages were present in the lamina propria of AIDS patients." (PMID 26475133, 2015). "In the absence of LPS, unstimulated total MMC from AIDS patients secreted significantly higher levels of macrophage related pro-inflammatory cytokines (TNF-α and IL-6) and chemokines (CCL2, CXCL10) compared to the MMC isolated from healthy controls." (PMID 26475133, 2015). "To determine whether macrophages were contributing to the pro-inflammatory milieu in the colon of AIDS patients, we performed double labeling of CD68+ macrophages with TNF-α and IL-1β using a dye swap method with validation by fluorescence microscopy." (PMID 26475133, 2015). "In AIDS patients, the TNF-α synthesis is not affected since monocytes are the major source this cytokine in response to soluble T. gondii antigens." (PMID 25352834, 2014). "Elevated catabolic chemokines such as TNF-α, IL-1, IL-6 and interferon which are thought to be responsible for inflammation induction have been documented in AIDS patients without evidence of any secondary infection." (PMID 24198891, 2013).
AIDS (continued). "Collectively, our data showed for the first time that, HIV-1 Tat interacts physically with high affinity with TLR4-MD2 to promote proinflammatory cytokines (TNF-α) and the immunosuppressive cytokine IL-10 both involved in immune dysregulation during early HIV-1 infection and AIDS progression." (PMID 24165011, 2013). "These high levels of TNF-α contribute to fever, anorexia, and other symptoms of HIV/AIDS." (PMID 22242038, 2012). "It has been shown that TNF-α mRNA level in the subcortical regions of HAD patients' CNS are higher than in AIDS patients without neurological symptoms." (PMID 16712719, 2006). "Not only the level of pro-inflammatory cytokines, such as TNF-α, IL-1 and IFN-γ, anti-inflammatory cytokines including TGF-β and IL-6, and soluble cytokine receptors is elevated in AIDS patients, but the cytokine production is correlated with the gravity of the neuropathology." (PMID 16712719, 2006). "In this study we determined that chronic HIV-1 transgene expression in rats, which causes a progressive systemic illness that recapitulates many of the manifestations of AIDS in humans, increases the expression of the pro-inflammatory cytokine TNFα in the liver but not in the lung." (PMID 21978457, 2011). "However, whether TNFα is involved in the development of neuropathic pain in the HIV/AIDS patients is not clear." (PMID 21599974, 2011). "Elevated in subjects with with a previous diagnosis of AIDS.Positive correlation between CSF cf-mtDNA with better neurocognitive performance, MCP-1, TNF-α, IL-8.Negative correlation with CD4+ T-cell nadir." (PMID 37762464, 2023). "In support of the protective role of proinflammatory cytokines, a later study also showed that HIV/AIDS patients who have survived cryptococcal meningoencephalitis exhibited higher CSF levels of IL-8, IL-12p40, IL-17A, TNF-α, INF-γ and serum TNF-α compared to non-survivors." (PMID 36557672, 2022). "The use of tumor necrosis factor inhibitors (TNFi) has been a topic of discussion in the context of patients with ReA and HIV, although it has been suggested that it may be safe in patients who do not have AIDS and have been refractory to conventional DMARDs." (PMID 39429408, 2024).